FOXP3 (forkhead box P3)
Diseases named in the same sentence as FOXP3 in open-access papers (continued):
Sharing a sentence is not in itself a finding about the gene and the disease.
infection (continued). "If one assumes that all FoxP3+ cells, regardless of CD25 expression, have the same frequency of infection as CD25hiFoxP3+ CD4+ T cells, one can estimate the relative size of the Treg reservoir as potentially ranging from 3.1 to 38.6% of the total resting CD4+ T cell reservoir." (PMID 18827929, 2008). "Thus, the increment in CD25+ cells during infection is not accompanied by preferential Foxp3 induction and represents an expansion of both CD4+CD25+Foxp3+ and CD4+CD25+Foxp3– T cells." (PMID 17563918, 2007). "Herein, neither FoxP3 expression by CD3highCD4+ T-cells nor the tTreg frequency changed upon in vitro HIV infection alone or in combination with TGF-β1 treatment, suggesting that thymocyte infection with HIV does not affect FoxP3 expression by CD4 T-cells or tTreg differentiation." (PMID 37547675, 2023). "Similarly, there was no increase in Foxp3 MFI iLN, or spleen during the first 3 weeks of infection." (PMID 26195548, 2015). "In contrast, following infection of C57BL/6 mice with the L. major strain NIH/Sd, which produces nonhealing dermal lesions in a Th1-polarized setting, it was shown that IL-10-producing CD4+ CD25− FoxP3− Th1 cells rather than Treg cells are the major contributors to immune suppression." (PMID 23825956, 2013). "However, infection status did not alter the in vitro suppressive ability on a per-cell basis of CD4+CD25+Tregs from the mLN, indicating that infection-expanded CD4+FoxP3+Tregs and those from naïve mice share a common mechanism of Th2-effector cell suppression." (PMID 21858239, 2011). "However, contrary to what has been reported in other parasite models, we did not detect an increased proportion of FoxP3+ CD4+ T cells in the LI LP at this infection dose, but rather a substantial decrease, a change that was apparent already at day 20 and remained as the infection progressed." (PMID 25942314, 2015).
inflammation (40 papers, 2010 to 2025). Aberrant reaction of the microcirculation characterized by movement of fluid and leukocytes from the blood into extravascular tissues. "Foxp3+CD4+ regulatory T cells are instrumental in enforcing homeostasis at the intestinal barrier surface as illustrated by the development of intestinal inflammation in diseases caused by a primary deficiency in the number or function of Treg cells in the gut." (PMID 34262567, 2021). "These cell changes result in enhanced IL-17 and IL-6 expression but reduced Foxp3 and IL-10 expression in the renal tissues of LN mice, which are significant risk factors for the occurrence of renal inflammation and underlying causes for developing renal damage." (PMID 31488076, 2019). "Whereas CD4+Foxp3+ cells regulate inflammation-mediated tissue damage, this aspect has not been addressed during chronic tuberculosis, the hallmark of which is the perpetuation of lung inflammation." (PMID 30584243, 2018). "Thus, the application of a Treg therapy in a disease of chronic inflammation could lead to a loss of FOXP3." (PMID 41235222, 2025). "CD4+CD25+FoxP3+ regulatory T cells interact with cells of both the innate and adaptive immune systems to limit acute lung inflammation and promote its resolution." (PMID 41463029, 2025). "The prototypic member, TGM1, induces in vitro differentiation of Foxp3+ T regulatory cells and attenuates airway allergic and intestinal inflammation in animal models." (PMID 40302223, 2025). "FOXP3+Treg can promote the normal proliferation and differentiation of lung epithelial cells, inhibit lung inflammation, and resolve acute lung injury." (PMID 38491484, 2024). "Studies showed that LP CD4+ T cells secrete cytokines associated with the development of intestinal inflammation, whereas regulatory T (CD4+CD8a−CD25+Foxp3+) cells in the LP can inhibit cytokine production and the development of intestinal inflammation." (PMID 31370803, 2019). "Because CCR4 induces the recruitment of regulatory T cells to the lung, we used CCR4-deficient (CCR4−/−) mice as a tool to address the role of CD4+Foxp3+ T cells in the chronic lung inflammation induced during M. tuberculosis infection." (PMID 30584243, 2018). "It is not clear if this reduction in the number of T cells at early stages of airway inflammation correlates with a regulatory T-lymphocyte phenotype (CD4+ CD25+ FoxP3+) in a model of pathogen-mediated inflammation in the colon." (PMID 27795621, 2016). "Previous work showed that Foxp3+ Treg regulates the development of silica-induced lung inflammation and fibrosis by modulating the Th immune response." (PMID 27354007, 2016). "Additionally, Exo-d-MAPPS promoted the expansion of immunosuppressive IL-10-producing alternatively activated macrophages, regulatory DCs, and CD4+FoxP3+T regulatory cells in inflamed lungs which resulted in the attenuation of chronic airway inflammation." (PMID 32257769, 2020). "The immunostaining of mice lung tissue sections from the same experimental groups verifies that SAHA induces expression of FoxP3+ cells (white arrows), suggesting an increase in the number of T-regs as a mechanism to suppress Pa-LPS induced pulmonary inflammation." (PMID 29301535, 2018). "Collectively, these data indicate that iNKT cells play a critical role in regulating Foxp3 expression by CD25+CD4+ T cells and thereby determine the fate of these CD25+CD4+ T cells into either protective or pathogenic ones during DSS-induced intestinal inflammation." (PMID 36499642, 2022). "Indeed, in IBD patients, Foxp3+IL-17-producing Treg cells are observed in the inflamed intestines tissues compared with their slightly or non-inflamed counterparts, which suggests the involvement of Treg plasticity and Foxp3+IL-17-producing Treg cells in intestinal inflammation pathogenesis." (PMID 36077306, 2022).
inflammation (continued). "In animal models of intestinal inflammation, CCK suppresses Th1 and Th17 differentiation, enhances Th2 cytokine production, and induces regulatory T cells expressing forkhead box protein P3 (FOXP3), through both CCK-1R and CCK-2R." (PMID 40723884, 2025). "Conjunctival inflammation in acute forms of ocular allergy has increased CCR4+CCR9+ effector T cells, with a diminished frequency of CD4+CD25+FOXP3+ regulatory T cells in peripheral blood." (PMID 33114004, 2020). "Cats dually sensitized to both Bermuda grass allergen and house dust mite given AIT to either allergen displayed decreased eosinophilic airway inflammation and higher levels of CD4+ CD25+ FoxP3+ Treg cells compared to placebo-treated cats." (PMID 28056956, 2017). "We have reported that Foxp3 molecule is more easily induced in the mLN than in the spleen, but in the food-allergic intestinal inflammation model like Rag23−3 or OVA23−3 mice, this is not necessarily the cases." (PMID 40446078, 2025). "Unlike responses in the small intestine, the absence of Il4ra on T reg cells only modestly reduced the frequency of ex-Foxp3 Th2 cells, suggesting that IL-4R–independent mechanisms also contribute to T reg cell conversion after acute HDM-driven airway inflammation." (PMID 28507062, 2017). "In addition, these mφ seem to facilitate secondary expansion and maintenance of antigen-specific Foxp3+ Treg cells through IL-10 production and consequently, to regulate TNBS-induced intestinal inflammation." (PMID 27576902, 2016). "Our study provides clear evidence that irrespective of the cause of liver damage, Foxp3 expression, and not IL-10 and TGF-β1, appeared with a dramatic increase that relates to the intensity of liver inflammation." (PMID 21772667, 2011). "C57BL/6 mice did not develop lung inflammation and presented higher frequency of CD4+CD25+Foxp3+ Treg cells in the bronchoalveolar lavage fluid (BALF) after the allergen challenge." (PMID 34924814, 2021). "In the absence of IL-4Rα responsiveness on FoxP3+ Tregs, exacerbated AHR and airway inflammation were shown in HDM-sensitized mice." (PMID 32931477, 2020). "However, it is not yet clear whether the accumulation of cytosolic DNA, potentially resulting from autoimmune inflammation, triggers changes in the cellular localization of Ku70, thereby influencing the immunosuppressive function of Tregs in a manner that is independent of FOXP3." (PMID 39446493, 2024).
adenocarcinoma (31 papers, 2009 to 2026). A common cancer characterized by the presence of malignant glandular cells. "TGFβ1 and TGFβ2 have been implicated in FOXP3 induction in peripheral Tregs and adenocarcinoma expansion." (PMID 36973425, 2023). "A high number of intratumoral and stromal Foxp3 TILs were significantly associated with adenocarcinoma." (PMID 36662367, 2023). "The YTHDF1 or YTHDF2 mRNA expression was significantly negatively associated with CD4, CD8, and FOXP3 mRNA expression in adenocarcinoma." (PMID 36479088, 2022). "Additionally, the enrichment of Foxp3+ Tregs was associated with a drastic decrease of NK cells in adenocarcinoma samples and metastatic lymph nodes." (PMID 33230935, 2021). "Additionally, our analysis showed that high levels of FoxP3+ regulatory T cells are thought to play protumor roles, and their significant association with greater rates of recurrence has been shown for adenocarcinoma." (PMID 26871598, 2016). "To address this, we transplanted FoxP3.Luci-DTR + CD27 − / − mixed bone marrow chimeric mice subcutaneously with MC38 adenocarcinoma cells." (PMID 34423375, 2022). "Due to the significant difference in the distribution of FOXP3(+) cells in cervical squamous carcinoma and adenocarcinoma, we further compared the OS and PFS of the four groups in the two disease types, respectively." (PMID 31842422, 2019). "Although both major types of NSCLC contributed to an increase in plasma anti-CD25a and anti-FOXP3 IgG levels, decreased anti-CD25b IgG levels were observed only in patients with adenocarcinoma (Z = −4.22, P < 0.001)." (PMID 29959381, 2018). "We observed significant differences of Foxp3/CD8 ratio between metastatic versus free LNs only in adenocarcinoma." (PMID 28831395, 2017). "We found a significantly lower proportion of CD8+ cells and a significantly higher Foxp3+/CD8+ ratio in LNs affected by adenocarcinoma versus LNs free of metastases." (PMID 28831395, 2017). "In a previous study including stage I adenocarcinomas, tumors containing high stromal FOXP3+ and low stromal CD3+ were considered to be more progressive, and FOXP3+ high versus stromal CD3+ low was found to be a strong predictor of recurrence." (PMID 27463005, 2016). "Treatment with anti-CD25 antibody decreased splenic Foxp3+CD25+ cells by 95%, decreased lung-associated Foxp3+ cells by 65% and decreased the multiplicity of IO33 adenocarcinomas by 80%." (PMID 19330036, 2009). "In adenocarcinoma, YTHDF2 was negatively correlated with CD4 and CD8 and positively correlated with FOXP3 in protein and mRNA analysis." (PMID 36479088, 2022). "According to our data, for adenocarcinomas and NSCLC in general, FOXP3 cannot serve as a reliable prognostic criterion." (PMID 32933105, 2020). "For fifteen patients with adenocarcinoma, more distinctive patterns were observed in CD3+ (P = 0.078), CD8+ (P = 0.055), FOXP3+ (P = 0.016), and PD-1+ (P = 0.016) TILs." (PMID 30616523, 2019). "Aggressive and invasive K-Ras-induced adenocarcinomas (IO33 and K-RasLA2) remained sensitive to more direct targeting of Foxp3+ cells through a neutralizing anti-CD25 antibody or genetic deletion." (PMID 19330036, 2009). "Representative figures of immunohistochemistry in adenocarcinoma show that high YTHDF1 or YTHDF2 cases are associated with low CD4, CD8 and high FOXP3 expression in both PD-1 inhibitor treatment and non-treatment groups." (PMID 36479088, 2022). "Increased numbers of Foxp3+ T cells have been found in the gastric mucosa of H. pylori infected adenocarcinoma patients in comparison to non-infected individuals." (PMID 20209161, 2010). "Potentially immunoregulatory CD8+FOXP3+ T cells and immune-dysfunctional CD8+GATA3+ T cells are increased in adenocarcinoma of non-smokers." (PMID 36091058, 2022). "CD4+FOXP3+ regulatory T cells expressing CCR4 and CCL17-expressing CD163+ M2-like macrophages also accumulated correlatively and significantly in adenocarcinoma of non-smokers." (PMID 36091058, 2022).
adenocarcinoma (continued). "A high FOXP3/CD4 ratio and a low number of CD20+ B cells were identified as negative prognostic factors in adenocarcinomas." (PMID 33230935, 2021).
infectious disease (28 papers, 2008 to 2024). A disorder directly resulting from the presence and activity of a microbial, viral, or parasitic agent in humans. "Studies have found an association between common gene polymorphisms in FoxP3 and some infectious diseases." (PMID 29020928, 2017). "On the contrary, infectious diseases such as tuberculosis have consistently demonstrated higher frequencies of FOXP3 in peripheral blood." (PMID 35227196, 2022). "Another important question therefore is whether the in vitro induced FoxP3 Treg cells have similar regulatory functions in human TB and other infectious diseases as the naturally occurring Treg cells." (PMID 23826366, 2013). "FOXP3 will express CD4+ CD25+ T-regulatory cells (Tregs), the key regulators of mucosal immune responses that play a role in chronic inflammation and infectious diseases." (PMID 35227196, 2022). "Based on Foxp3 CNS1 similarities in human and mouse, it is plausible that FOXP3 CNS1 plays a role in the control of human infectious diseases." (PMID 35812386, 2022). "A definitive study of the function of Foxp3, in either CD4 or γδ T-cells, to demonstrate their specific actions within veterinary infectious disease remains to be completed." (PMID 28871261, 2017). "And the elevation of Foxp3+ DNT cells might act as negative feedback to ameliorate pathogenesis in infectious diseases." (PMID 35967422, 2022).
bacterial infection (9 papers, 2014 to 2024). "Beyond targeting tumors, suppressing FOXP3 in PD1+ T cells may also be useful in addressing immunological anergy associated with bacterial infections." (PMID 39772246, 2024). "Here, we show using bacterial infection and antigen challenge models that extrathymic Foxp3+ regulatory T-cells that arise de novo in the context of bacterial infection require an intact eosinophil compartment." (PMID 35169233, 2022). "Neither previous rejection nor previous viral or bacterial infection were associated with the Foxp3 TSDR methylation status of enriched IFNy+ or IFNy- Treg (p>0.05; Fisher ́s exact test)." (PMID 28296931, 2017). "In a murine model of burns with bacterial infection, APS was found to suppress the expression of Foxp3 by CD4+CD25+ Treg and to activate Th1 cell-mediated immunity." (PMID 26693207, 2015). "However, we did not observe changes in the levels of ROR-γt and Foxp3 proteins, probably because the young mice used in this study had strong immunity against bacterial infection." (PMID 35756539, 2022). "SPY1 vaccination activated Foxp3, increasing the frequency of CD4+CD25+Foxp3+ Tregs during vaccination; SPY1 elevated Smad2/3 and phosphor-Smad2/3 downregulated a negative signal by Smad7 during live bacterial infection (Smad 1–9 regulate TGF-β receptor signaling)." (PMID 39340024, 2024).
cardiovascular disease (7 papers, 2016 to 2023). "Finally, FOXP3 isoform profile has been linked to cardiovascular diseases." (PMID 34768829, 2021). "Therapeutic adoptive transfer of natural regulatory T cells (nTreg, CD4+ CD25+ Foxp3+ T cells) or in vivo selective expansion of nTreg cells has been demonstrated to improve the cardiac function in various cardiovascular disease models." (PMID 30770790, 2019). "Or does Foxp3 instability have a similar toxic effect on cardiovascular disease?" (PMID 36911741, 2023). "Furthermore, the percentages of peripheral CD4 + CD25 + Foxp3 + Treg and serum IL-10 level were influenced by diabetic complications such as cardiovascular diseases." (PMID 29051757, 2017).
kidney disease (7 papers, 2017 to 2024). "Up to 25% of patients with FOXP3 mutations develop kidney diseases, including interstitial nephropathy and membranous glomerulonephritis, and kidney involvement could be the first manifestation of the disease." (PMID 38772735, 2024). "Two patients with kidney diseases due to FOXP3 mutations were treated with HSCT." (PMID 38772735, 2024). "Interestingly, the Foxp3 mRNA levels also correlated with the activity index in kidney biopsies and was proposed as a biomarker for active renal disease." (PMID 37368057, 2023). "The focus of this review has been on the role of CD4+ Foxp3+ Tregs in renal disease." (PMID 29484182, 2018). "Although CD4+ Foxp3+ Tregs can confer protection in many kidney diseases, the functional role of transcription factor Foxp3 in GN has not been fully explored, and the mechanism whereby Foxp3 regulates autoimmune kidney disease remains to be elucidated." (PMID 28469165, 2017).
neurological disorders (7 papers, 2014 to 2024). "Our results highlight the preponderant role, at the expression level, of IL-17 and regulatory markers IL-4, IL-10, and Foxp3 in the blood as the major contributors to the segregation of the two studied neurological disorders." (PMID 33719347, 2021). "It has been previously demonstrated that subjects with symptomatic WNV infections have decreased numbers of CD4+ CD25+ Foxp3+ Treg cells and mice depleted of Tregs have increased neurological disease and mortality." (PMID 26795118, 2016). "This suggests that CD4+Foxp3+ Tregs elicit dual-phased roles during the progression of JEV-induced neurological disorders." (PMID 25188232, 2014). "Regulatory T (Treg) cell differentiation and function are driven by the FOXP3 transcription factor, and the expression of FOXP3 has been shown to be decreased in individuals who develop neurologic diseases; for example, a decreased frequency of Treg cells has been found in children with ASD." (PMID 33671196, 2021).
gastrointestinal tumor (6 papers, 2013 to 2024). "We further found NOTCH3 levels in gastrointestinal tumor to correlate with markers of Dendritic cell(HLA-DPB1, HLA-DRA, HLA-DPA1, BDCA-4), Tfh(T-bet, STAT4, STAT1, TNF-α), Treg cells (FOXP3, CCR8, STAT5B, TGFβ) and T cell exhaustion (PD-1, CTLA4, LAG3, TIM-3)." (PMID 38906903, 2024).
hematologic malignancies (6 papers, 2011 to 2025). "In line with this, FOXP3 gene mutations have been associated with various autoimmune and hematological disorders, and Treg loss of FOXP3 has been shown to result in the acquisition of effector properties by these cells, with the production of pro‐inflammatory cytokines." (PMID 34375446, 2021). "Its unique ability to inhibit CK-1ε helps to maintain the number and function of regulatory T-cell in patients via the TCF-1 and FoxP3 pathway, reducing immune-mediated side effects in the treatment of hematologic malignancies." (PMID 41568384, 2025). "In particular, we investigated the ability of MDS and AML patient-derived MSCs to induce CD4+/CD25+/FoxP3+ cells, that is, regulatory T cells (Tregs), which are known to suppress immunity also in hematological malignancies." (PMID 30359303, 2018). "Tregs, a critical subset of CD4+ T cells that are characterized by the CD4+CD25+FoxP3+ phenotype, play the role of negative immune regulation in solid tumors and hematological malignancies." (PMID 36439426, 2022).
head and neck tumor (4 papers, 2014 to 2023). "Therefore, we analyze the spatial patterns of CD8+, FoxP3+, and CD68+ cells across whole slide images taken from 16 head and neck tumors." (PMID 34625491, 2021). "In this study, we assessed the presence and prognostic value of CD3, CD4, CD8, FoxP3, and PD1 positive TILs, as well as the CD8/FoxP3 ratio, in the head and neck tumor epithelium in pre-treatment biopsies of HNSCC patients using an objective, digital pathology-aided method." (PMID 31980916, 2020).
benign tumors (3 papers, 2014 to 2024). "The CD4+ cells correlated with the FOXP3+ cellular infiltrates within the benign tumors." (PMID 29137242, 2017).